CAV1 (caveolin 1)
Diseases named in the same sentence as CAV1 in open-access papers (continued):
Sharing a sentence is not in itself a finding about the gene and the disease.
autoimmune disease (2 papers, 2018 to 2025). A disorder resulting from loss of function or tissue destruction of an organ or multiple organs, arising from humoral or cellular immune responses of the individual to their own tissue constituents. "Enhanced autophagy activity reduces the production of proinflammatory cytokines in RA FLSs, while heat shock proteins (HSPs) and caveolin-1 protect against autoimmune diseases in an autophagy-related way." (PMID 30538709, 2018).
autoimmune hepatitis (2 papers, 2023 to 2025). Hepatitis caused by autoantibodies. "Research indicates that the downregulation of CAV1 is accompanied by ferroptosis in autoimmune hepatitis." (PMID 40180904, 2025). "Our previous study found that Cav-1 alleviated liver injury in autoimmune hepatitis by inhibiting iron accumulation in the liver." (PMID 37941054, 2023). "Our previous study confirmed that Cav-1 alleviates ferroptosis in autoimmune hepatitis by suppressing hepatic iron accumulation." (PMID 37941054, 2023). "Furthermore, our previous study demonstrated that Cav-1 can inhibit liver iron metabolism dysfunction in autoimmune hepatitis." (PMID 37941054, 2023).
autoimmune uveitis (2 papers, 2021 to 2025). An autoimmune form of uveitis (disease). "Recent studies have suggested a link between Cav‐1 and various ocular diseases, such as autoimmune uveitis, primary open‐angle glaucoma, and diabetic retinopathy." (PMID 40778471, 2025).
bacteremia (2 papers, 2019 to 2023). "In conclusion, our study indicates that P. gingivalis bacteremia may promote the permeability of BBB in BMECs by the Mfsd2a /Cav-1-mediated transcytosis pathway." (PMID 36631446, 2023).
Berardinelli-Seip congenital lipodystrophy type 3 (2 papers, 2015 to 2025). "Mutations in CAV1, encoding the main component of the caveolae in plasma membranes, cause Berardinelli-Seip congenital lipodystrophy type 3 (BSCL)." (PMID 26176221, 2015).
breast adenocarcinoma (2 papers, 2007 to 2020). "They observed that motile mammary adenocarcinoma cells failed to express normal levels of caveolin-1, in contrast to their non-motile counterparts." (PMID 18949068, 2007).
breast ductal carcinoma (2 papers, 2016 to 2021). "Here, we demonstrate that the reconstitution of Cav-1 expression in invasive MCF7 breast ductal carcinoma cells that are normally deficient in Cav-1 suppresses glycolysis and enhances mitochondria-dependent ATP production." (PMID 26543228, 2016). "In fact, the reconstitution of Cav-1 expression in invasive MCF7 ductal carcinoma cells effectively reduced MnSOD expression and steady state H2O2 levels." (PMID 26543228, 2016).
bronchopulmonary dysplasia (2 papers, 2020 to 2021). Bronchopulmonary dysplasia is a chronic respiratory disease that results from complications related to lung injury during the treatment of infant acute respiratory distress syndrome in low-birth-weight premature infants or from abnormal lung development in older infants. "However, disruption of ECs and endothelial caveolin-1 loss accompanied by enhanced expression of caveolin-1 in SMCs was observed in infants with bronchopulmonary dysplasia, associated with inflammation and PH." (PMID 34698188, 2021). "Extensive loss of endothelial CAV1 accompanied by enhanced expression of CAV1 in vascular smooth muscle cells (VSMC) was reported in IPAH, in HPAH, in PAH associated with congenital heart defect and drug toxicity, and in infants with bronchopulmonary dysplasia and evidence of inflammation." (PMID 31979420, 2020).
Cachexia (2 papers, 2018 to 2019). Severe weight loss, wasting of muscle, loss of appetite, and general debility related to a chronic disease. "Our prediction analyses also revealed microRNA miR-17 as an important regulator of transcripts, such as Cxcl12, Mef2c, Stat3, and Cav1, that are translated into proteins with a role in cancer cachexia." (PMID 31013615, 2019).
cataract (2 papers, 2023 to 2025). Partial or complete opacity of the crystalline lens of one or both eyes that decreases visual acuity and eventually results in blindness. "On a rare occasion of CAV1-encoding gene mutation affecting siblings of one boy and one girl, only the boy developed cataracts, suggesting the likelihood that CAV1 has a superior role in protecting males against cataracts, in parallel to current results." (PMID 40649110, 2025). "Increased expression of CAV1 is closely related to vesicle transport and cell cycle regulation, and affects the function of LECs, which may lead to the occurrence of cataracts." (PMID 37131205, 2023). "Compared with the ARC group, the levels of CTGF, FOS, CAV1, CYR61, ICAM1, EGR1, and NR4A1 in the anterior capsule of PACG patients with cataracts were upregulated, which was consistent with the sequencing data." (PMID 37131205, 2023).
congestive heart failure (2 papers, 2020 to 2022). Failure of the heart to pump a sufficient amount of blood to meet the needs of the body tissues, resulting in tissue congestion and edema. "That supports the relevance that caveolin-1 might have in other causes of CES as symptomatic congestive heart failure with reduced ejection fraction, or its importance in ESUS as a marker of an occult FA or left ventricular disfunction, which could benefit from anticoagulant treatment." (PMID 35872910, 2022).
cytomegalovirus infection (2 papers, 2017 to 2025). A herpesvirus infection caused by Cytomegalovirus. "Nevertheless, HCMV infection with AD169 did reduce the steady state levels of caveolin-1 as well as CD98, CD44, and CD81 as shown by Western blotting of whole cell lysates." (PMID 29121670, 2017).
deafness (2 papers, 2019 to 2020). An inherited or acquired condition characterized by the complete loss of the ability to hear from one or both ears. "The importance of both Cav1 L-type Ca2+ channels during sensory signaling gets obvious after its ablation, either by recombinant technologies for Cav1.3, leading to deafness or after native gene loss for Cav1.4 leading to night blindness." (PMID 32375703, 2020). "In this study, about 10% of the IHCs in cKO-Cav1.3flex/- mice carried an unswitched flex allele resulting in residual hearing function compared with complete deafness of Cav1.3-/- mice." (PMID 31178698, 2019).
diabetic neuropathies (2 papers, 2020 to 2023). "However, a link between CAV1 and diabetic neuropathies is not well established." (PMID 32082483, 2020).
diabetic retinopathy (2 papers, 2017 to 2023). "After detecting vascular regression in 8-month-old Cav-1+/− retinas, we further analyzed neuronal changes in these retinas by PAS staining, since neuronal and vascular damage are often coupled in the NVU in pathological conditions, such as diabetic retinopathy." (PMID 37923999, 2023).
diffuse large B-cell lymphoma (2 papers, 2018 to 2023). "Using publicly available microarray data we examined the expression of CAV1 in tumor biopsy samples from FL and two established subtypes of diffuse large B-cell lymphoma (DLBCL), comparing them to normal SP controls." (PMID 30005686, 2018).
Fibroadenoma (2 papers, 2007 to 2021). A benign tumor of the breast characterized by the presence of stromal and epithelial elements. "In both Sorlie Breast statistics and Sorlie Breast 2 statistics, the lower expression of CAV1 was most prominent in fibroadenoma, with a fold change of -14.128 and -12.864 respectively." (PMID 34513683, 2021). "Caveolin-1 expression could be determined in 236 of 295 cases of benign breast disease (80.0%); in detail, 148 of 167 cases of fibroadenoma (88.6%), 65 of 93 cases of sclerosing adenosis (69.9%), 21 of 33 cases of ductal hyperplasia (63.6%) and both cases of radial scar (100%) could be evaluated." (PMID 17915016, 2007).
follicular adenoma (2 papers, 2002 to 2023). "Bioinformatics studies have shown that CAV1 is a common hub gene that plays an important role in the occurrence and development of parathyroid and thyroid follicular adenomas." (PMID 37907864, 2023). "We also examined caveolin-1 expression in tumours of follicular type, that is, 11 cases of follicular adenoma, 18 cases of minimally invasive follicular carcinoma and 15 cases of widely invasive follicular carcinoma." (PMID 11953823, 2002).
frontotemporal lobar degeneration (2 papers, 2021 to 2023). "A summary of the proteomics data revealed enrichment of 330 proteins in UV light irradiated samples including known cholesterol binding proteins like caveolin-1 (CAV1) and Niemann-Pick disease, type C1 (NPC1), among others 43,44." (PMID 34981045, 2021).
gastric adenocarcinoma (2 papers, 2017 to 2020). "After analyzing the gastric adenocarcinoma expression data downloaded from TCGA database via Genomic Data Commons Data Portal, we found that high expression of Cav-1 was associated with lower survival of GC patients." (PMID 32117718, 2020). "Reduced levels of Cav-1 in human gastric adenocarcinoma cells resulted in significant STAT3 activation and enhanced cell proliferation." (PMID 29221162, 2017).
geographic atrophy (2 papers, 2020 to 2022). "Meanwhile, in the RPE cells of AMD patients, expression of caveolin-1 is significantly increased and promotes cellular senescence, thereby contributing to the progression of geographic atrophy in dry AMD." (PMID 36421712, 2022). "Nevertheless, in exchange for blocking subretinal fibrosis, caveolin-1 promotes RPE cellular senescence and might affect the progression of geographic atrophy in AMD." (PMID 32926104, 2020).
gestational diabetes (2 papers, 2020 to 2025). Carbohydrate intolerance first diagnosed during pregnancy. "During pregnancy, CAV1 has been associated with glucose and fatty acid transport in the placenta by inducing AMPK and reducing the GLUT1 signalling pathway and reversing macrosomia due to gestational diabetes (GD)." (PMID 32028606, 2020). "In gestational diabetes mellitus (GDM), chronic hyperglycemia suppresses the AMPK-mTOR-PIK3C3 pathway, thereby inhibiting CAVIN1-LC3B-mediated autophagic degradation of Cav-1, leading to Cav-1 accumulation." (PMID 41030451, 2025).
glomerular diseases (2 papers, 2021 to 2023). "However, the connection between Cav-1 and eNOS has rarely been discussed in studies about glomerular diseases." (PMID 37229256, 2023). "Although current studies suggest that Cav-1 may regulate the progression of glomerular associated diseases by endocytosing of macromolecules (cholesterol or albumin), the mechanism by which Cav-1 modulates the development of glomerular diseases requires further study." (PMID 34955837, 2021).
Hashimoto thyroiditis (2 papers, 2020 to 2025). An autoimmune disorder caused by the production of autoantibodies against thyroid tissue. "In the Hashimoto’s thyroiditis cell model treated with IL-1β and IFN-γ, the decreased expression of Cav-1 can inhibit the activity of autophagy and downregulate the expression of autophagy-related protein LC3B-II." (PMID 41030451, 2025). "have examined the thyroid tissue of patients with Hashimoto’s thyroiditis and have found that the expression of Th1 cytokines interleukin-1β (IL-1β) and interferon-γ (IFN-γ) is higher than that of healthy individuals, while the expression of Cav-1 is lower than that of healthy individuals." (PMID 41030451, 2025).
hemorrhage (2 papers, 2020 to 2021). Loss of blood from the vascular compartment to the exterior or into nonvascular body space as a result of rupture or severance of the blood vessels. "Both the serum levels of caveolin-1 and caveolin-2 in hemorrhage group (0.14 ± 0.025 and 0.46 ± 0.043 ng/ml, respectively) are lower than in non-hemorrhage group (0.39 ± 0.046 and 0.47 ± 0.051 ng/ml, respectively)." (PMID 33224083, 2020). "Our results showed that the non-hemorrhage group of patients presented significantly higher caveolin-1 and caveolin-2 levels than the hemorrhage group of patients after intravenous thrombolysis treatment." (PMID 33224083, 2020).
hypertrophic cardiomyopathy (2 papers, 2020). A condition in which the myocardium is hypertrophied without an obvious cause. "Loss of CAV-1 gene expression in mice has been also reported to cause the progression of hypertrophic cardiomyopathy and sudden cardiac death syndrome." (PMID 31948008, 2020). "Knockout mice for caveolin-1, caveolin-2, and caveolin-3 develop hypertrophic cardiomyopathy with increase in fibrosis." (PMID 32626662, 2020).
immune deficiency (2 papers, 2024 to 2025). "In addition, the downregulation of caveolin-1 (Cav1) protein further exacerbates this immune deficiency, by reducing lymphocyte activation and weakening the immune response, thereby diminishing the host’s ability to deal with Leishmania infection." (PMID 40808943, 2025). "Potentially, this could explain the association between high CAV1 expression and immunodeficiency in the TME observed in our study." (PMID 38959243, 2024).
influenza (2 papers, 2010 to 2017). An acute viral infection of the respiratory tract, occurring in isolated cases, in epidemics, or in pandemics; it is caused by serologically different strains of viruses (influenzaviruses) designated A, B, and C, has a 3-day incubation period, and usually lasts for 3 to 10 days. "To address the biological relevance of the interplay of Cav-1 with influenza proteins we performed inhibition experiments with a dominant-negative Cav-1 mutant, knock-down by Cav-1 RNAi as well as competition experiments with M2 fusion proteins." (PMID 20504340, 2010). "RNAi-mediated Cav-1 knock-down as well as transfection of a dominant-negative Cav-1 mutant results in a decrease in virus titre in infected Madin-Darby canine kidney cells (MDCK), a cell line commonly used in basic influenza research as well as in virus vaccine production." (PMID 20504340, 2010).
interstitial lung disease (2 papers, 2011 to 2015). A diverse group of lung diseases that affect the lung parenchyma. "The profibrotic effects of CAV1 deficiency are likely related to impaired TGF-β receptor degradation, however, CAV1 downregulation in SSc interstitial lung disease has also been reported to increase tissue fibrosis by influencing monocyte migration and recruitment." (PMID 25852818, 2015).
ischemia reperfusion injury (2 papers, 2018 to 2021). Adverse functional, metabolic, or structural changes in ischemic tissues resulting from the restoration of blood flow to the tissue (reperfusion), including swelling; hemorrhage; necrosis; and damage from free radicals. "Furthermore, caveolae and cav1 have been associated with tight junction organization in the cerebral endothelium and have been shown to impact blood brain permeability in ischemia reperfusion injury." (PMID 29760588, 2018). "Cav1 was also reported to inhibit nitrative stress-induced liver damage during hepatic ischemia-reperfusion injury." (PMID 34434195, 2021).
kidney stones (2 papers, 2022 to 2025). "Cav-1 and autophagy play a role in the occurrence and development of urinary system diseases such as prostate cancer (PCa), clear cell renal cell carcinoma (ccRCC), tubulointerstitial fibrosis and kidney stones." (PMID 41030451, 2025). "In a study on calcium oxalate (CaOx) kidney stones, it is speculated that CaOx promotes kidney stone formation by downregulating the Cav-1 and low density lipoprotein receptro-related protein 6 (LRP6)/Wnt/β-catenin pathways, causing autophagy dependent ferroptosis." (PMID 41030451, 2025). "This suggests that Cav-1-autophagy may be involved in the pathogenesis of kidney stones." (PMID 41030451, 2025). "We presumed that CAV1 could promote Wnt/β-catenin signaling pathway through up-regulating LRP6, then LRP6/WNT suppressed ferroptosis via alleviating autophagy of epithelium and finally decreased kidney stones formation." (PMID 36128191, 2022).
large cell carcinoma (2 papers, 2015 to 2019). A malignant epithelial neoplasm composed of large, atypical cells. "Regarding histology, tumor cells of ADC showed lower Cav-1 expression (high Cav-1 expression, 28%), whereas SQC and large cell carcinoma showed relatively higher levels of Cav-1 expression (52% and 59%, respectively)." (PMID 31297035, 2019).
macrosomia (2 papers, 2017 to 2020). "In order to further explore the role of Cav-1 in GDM-induced macrosomia, we analyzed the association of Cav-1 with the protein levels of GLUT1, p-AMPKα(Thr172) and p-ACC(Ser79)." (PMID 28125642, 2017). "The data we collected confirmed that GDM-induced macrosomia had the lowest mRNA and protein levels of Cav-1 and p-AMPK." (PMID 28125642, 2017). "Placenta of GDM-induced macrosomia had significantly lower protein levels of Cav-1 compared to both CON and GDMN groups (p<0.05)." (PMID 28125642, 2017). "In conclusion, our study showed that the protein and mRNA levels of Cav-1 were significantly inhibited in the placenta of GDM-induced macrosomia." (PMID 28125642, 2017). "Combined with the positive correlation between Cav-1 and p-AMPK, we conclude that Cav-1 can induce AMPK-mediated lipid metabolism to participate in GDM-induced macrosomia." (PMID 28125642, 2017). "Cav-1 is associated with placental glucose and fatty acid transport via the induction of AMPK signaling pathway and the reduction of GLUT1 signaling pathway to reverse GDM-induced macrosomia." (PMID 28125642, 2017). "Combining with negative relevant relations to NBW, it is reasonable to make a conclusion that Cav-1 may be involved in GDM-induced macrosomia via reduction of GLUT1-mediated glucose metabolism." (PMID 28125642, 2017). "GDM-induced macrosomias have more severe inhibition of Cav-1 expression in placenta." (PMID 28125642, 2017). "Moreover, Cav-1 may involve in GDM-induced macrosomia via the induction of AMPK-mediated placental fatty acid metabolism and the reduction of GLUT1-mediated placental glucose metabolism." (PMID 28125642, 2017).
migraine (2 papers, 2018 to 2023). "Some agents employed to treat hemiplegic migraine include calcium channel blockers like flunarizine and verapamil (CaV1-blocking and potentially CaV2-blocking at higher doses)." (PMID 30080864, 2018).
Moyamoya disease (2 papers, 2022 to 2025). Moyamoya disease (MMD) is a rare intracranial arteriopathy involving progressive stenosis of the cerebral vasculature located at the base of the brain causing transient ischemic attacks or strokes. "Consequently, RNF213 ubiquitinates Cav-1 at several N-terminal lysine residues through K48 and K63 linkages, although several Moyamoya disease-associated RNF213 mutations greatly reduce this polyubiquitination." (PMID 40497951, 2025).
Neonatal progeroid syndrome (2 papers, 2019 to 2025). "Wiedemann-Rautenstrauch Syndrome is a heterogeneous disorder caused by a pathogenic variant found in one of a few genes, including POLR3A, FBN1, CAV1, and SLC25A24." (PMID 40440483, 2025).
oral lichen planus (2 papers, 2021). Oral lichen planus is a chronic inflammatory oral condition of unknown aetiology characterized by T-cell-mediated chronic immune response and abnormal epithelial keratinization cycle. "Comparing the Cav-1 expression in an immunohistochemical examination of biopsies from patients with an oral lichen planus (OLP) with patients with OSCC, an increased Cav-1 expression in OSCC could be detected." (PMID 33774714, 2021).
ovarian disease (2 papers, 2019 to 2021). "Compared to previous literature, just phosphorylations of MARCKS and CAV1 identified in this study were already reported in ovary diseases." (PMID 31442208, 2019). "Our findings demonstrate that loss of Cav-1 expression in CAF-enriched stromal cells is a marker of malignant ovarian disease and suggest Cav-1 may be a therapeutic target for OvCa." (PMID 34813586, 2021).
ovarian serous carcinoma (2 papers, 2014 to 2021). "Immunohistochemistry revealed expression of caveolin-1 in normal and benign ovarian epithelial cells, but loss of expression in serous ovarian carcinomas." (PMID 25594072, 2014). "Our findings demonstrate a loss of stromal Cav-1 expression in ovarian serous carcinomas." (PMID 34813586, 2021).